TMEM243 (transmembrane protein 243)
Synonyms: MM-TRAG; C7orf23; MGC4175; MMTRAG
Tractability: Antibody: UniProt predicts a signal peptide or a membrane-spanning region. PROTAC: its protein half-life has been measured.
Gene: Protein-coding gene on chromosome 7 (87,196,158 to 87,220,597, reverse strand). Ensembl gene ENSG00000135185.
Subcellular location: Membrane
Gene Ontology:
Molecular function: protein binding
Cellular component: membrane
Genetic constraint (gnomAD): Loss-of-function variants: 10 observed, 7.37 expected, observed/expected ratio (o/e) 1.36, 90% interval 0.81 to 1.9. That is too few expected variants to judge how well the gene tolerates losing a copy. Missense variants: 122 observed, 114.08 expected, observed/expected ratio (o/e) 1.07, 90% interval 0.92 to 1.24. Synonymous variants: 62 observed, 45.72 expected, observed/expected ratio (o/e) 1.36, 90% interval 1.1 to 1.67.
Homologues: Orthologues: chimpanzee TMEM243 (100% identical), macaque TMEM243 (100% identical), dog TMEM243 (97% identical), mouse Tmem243 (97% identical), pig TMEM243 (97% identical), rabbit TMEM243 (96% identical), rat Tmem243 (95% identical), guinea pig TMEM243 (84% identical), zebrafish tmem243b (76% identical), zebrafish tmem243a (58% identical).
Diseases named in the same sentence as TMEM243 in open-access papers:
TMEM243 is named in the same sentence as 3 diseases in open-access papers, as found by Europe PMC text mining. Sharing a sentence is not in itself a finding about the gene and the disease. The quoted sentences say what the papers report.
lung carcinoma (1 paper, 2026). "In a panel of lung cancer cell lines with varying degrees of paclitaxel resistance, TMEM243 was also recognized as a paclitaxel resistance inducer whose expression rises in parallel with the loss of the tumor suppressor protein alpha-2-macroglobulin (A2M)." (PMID 41596760, 2026). "Thus, TMEM243 is a key downstream effector driving paclitaxel resistance in lung cancer and is negatively regulated by A2M." (PMID 41596760, 2026).
TMEM243 also shares sentences with these, for which no sentence is quoted: lung adenocarcinoma (1 paper); tumor (1).